OXTR (oxytocin receptor)
Diseases named in the same sentence as OXTR in open-access papers (continued):
Sharing a sentence is not in itself a finding about the gene and the disease.
Hypertension (4 papers, 2014 to 2023). The presence of chronic increased pressure in the systemic arterial system. "In another recent comprehensive review on the role of OXT and OXTR in cardiovascular diseases, it was stressed that the secretion of oxytocin is modulated in various conditions, including hypertension and myocardial infarction." (PMID 36835321, 2023). "Such a conclusion on the lack of considerable correlations between OXTR genotype and cardiovascular disease was corroborated in studies, indicating that the rs2268498 SNP in the OXTR gene is not a risk factor for hypertension." (PMID 36835321, 2023).
ovarian carcinoma (4 papers, 2016 to 2023). A malignant neoplasm originating from the surface ovarian epithelium. "Here, in addition to SNUC5/5-FUR, we determined that Nrf2 expression was higher in oxaliplatin resistant SNUC5 cells (SNUC5/OXTR) and cisplatin resistant ovarian cancer cells (A2780/CR) than in parental SNUC5 and A2780 cells, respectively." (PMID 27259240, 2016). "Several receptors have been found to be upregulated in ovarian cancer tissues, including growth hormone releasing hormone receptor (GHRHR), GRPR, leucine-rich repeat-containing G-protein coupled receptor 5 (LGR5), oxytocin receptor (OXTR) and parathyroid hormone 2 receptor (PTH2R)." (PMID 35625966, 2022).
perinatal depression (4 papers, 2020 to 2025). "Statistical testing did not support mediation of the association between insecure attachment style and perinatal depression by OXTR methylation." (PMID 32066670, 2020). "A detailed analysis of methylation density in the oxytocin receptor gene revealed similar patterns of DNA methylation in association with perinatal depression and with insecure attachment style, while childhood trauma was associated with a distinct methylation pattern in this gene." (PMID 32066670, 2020). "Similar patterns of methylation density were observed in association with perinatal depression and with insecure attachment style, and the inverse pattern with secure attachment style, whereas the pattern of methylation density within OXTR that was associated with childhood trauma was distinct." (PMID 32066670, 2020). "The CTQ and its subscales showed a distinct pattern of associations with methylation density within OXTR, one that was largely nonoverlapping with the pattern observed in association with perinatal depression." (PMID 32066670, 2020). "This suggests that OXTR specifically could be involved in the association between insecure attachment and perinatal depression, although methylation patterns in this gene were not sufficiently tightly clustered for it to be identified in our screen." (PMID 32066670, 2020). "Alternatively, OXTR methylation may be independently associated with both perinatal depression and attachment insecurity while not being directly involved in the association between them." (PMID 32066670, 2020). "The gene that codes for the oxytocin receptor (OXTR) is susceptible to stress-related epigenetic regulation of gene expression, and that mothers with perinatal depression have elevated DNA methylation at OXTR compared with mothers with no perinatal depression." (PMID 38834917, 2025).
post-traumatic stress disorder (4 papers, 2022 to 2025). An anxiety disorder precipitated by an experience of intense fear or horror while exposed to a traumatic (especially life-threatening) event. "The aims of this study were: (a) to examine associations of oxytocin receptor gene (OXTR) single nucleotide polymorphisms (SNPs) with post-traumatic stress disorder (PTSD) and dissociative symptoms and (b) to investigate gene–environment (G × E) interaction with childhood maltreatment." (PMID 35656579, 2022). "It was shown that the cumulative genetic risk, estimated by the contribution of five alleles, associated with a high risk of development of post-traumatic stress disorder (PTSD), of which three SNPs were variants of the oxytocin receptor gene, determined the dynamics of DMN development with age." (PMID 39421629, 2024). "Moreover, patients with ASD, post-traumatic stress disorder (PTSD), attention-deficit hyperactivity disorder (ADHD), or other psychiatric disorders showed conspicuous variations in the OXTR gene." (PMID 37153633, 2023).
type 2 diabetes (4 papers, 2016 to 2024). "Variants in OXTR gene have been associated with overeating, increased cardiovascular risk, and type 2 diabetes (T2D)." (PMID 37047255, 2023). "OT-R levels are higher in Type 2 diabetes, and there is an association of OXTR variants with insulin sensitivity and Type 2 diabetes." (PMID 38594674, 2024).
anorexia nervosa (3 papers, 2014 to 2018). A disorder most often seen in adolescent females characterized by a refusal to maintain a minimally normal body weight, an intense fear of gaining weight, a disturbance in body image, and, in postmenarcheal females, the development of amenorrhea. "Oxytocin receptor single nucleotide polymorphisms rs2254298 or rs53576 and neural responses to social stimuli were evaluated in adult women with or recovered from anorexia nervosa using functional magnetic resonance imaging." (PMID 30542304, 2018). "Epigenetic misregulation of the OXTR gene may be implicated in anorexia nervosa, which may either be a mechanism linking environmental adversity to risk or may be a secondary consequence of the illness." (PMID 24523928, 2014). "This pilot study suggests that in anorexia nervosa, differences related to OXTR SNP rs2254298 may alter neural responses to social stimuli and disrupt the engagement and disengagement of the default mode network." (PMID 30542304, 2018). "We examined whether there was evidence of variation in methylation status of the oxytocin receptor (OXTR) gene in patients with anorexia nervosa that might account for these findings." (PMID 24523928, 2014).
cognitive decline (3 papers, 2020 to 2024). "OXT and artificially developed OXTR agonists have potential as a therapeutic agent to improve the cognitive decline associated with HFD." (PMID 32719656, 2020). "Intranasal OXT administration can mitigate sensory–motor dysfunction and cognitive decline due to ICH, reducing inflammation via the OXTR/p-PKA/DRP1 signaling pathway." (PMID 38654385, 2024).
colon adenocarcinoma (3 papers, 2021 to 2024). "The increased level of OXTR mRNA may indicate a poor prognosis for patients with colon adenocarcinoma." (PMID 37713112, 2024).
emotional dysregulation (3 papers, 2014 to 2016). "The interactive effects of childhood maltreatment and the OXTR SNP rs53576 on adult emotional dysregulation and attachment style were investigated in a sample of low-income, African American men and women." (PMID 24596569, 2014). "Significant interactive effects were found between childhood maltreatment and OXTR rs53576 in predicting levels of adult emotional dysregulation and attachment style." (PMID 24596569, 2014).
endometrial cancer (3 papers, 2017 to 2018). Primary or metastatic malignant neoplasm involving the endometrium (mucous membrane that lines the endometrial cavity). "Oxytocin may play a regulatory role in tumor growth 30, and the presence of the oxytocin receptor in endometrial cancer cells represents a key factor in endometrial cancer progression." (PMID 29665298, 2018). "Importantly, an over-expression of oxytocin receptor was detected in endometrial cancer patients, thus indicating the clinical relevance of the oxytocin pathway in endometrial cancer progression." (PMID 30314310, 2018).
glioma (3 papers, 2022 to 2024). A benign or malignant brain and spinal cord tumor that arises from glial cells (astrocytes, oligodendrocytes, ependymal cells). "Since the previous studies have explored the role of the signature genes METTL7B, SSTR2, OXTR, CDKN2C, and H19 in glioma, while TNFRSF11B has been poorly studied, we examined the functional impact of TNFRSF11B on LGG cell behavior." (PMID 37713112, 2024).
Hyperglycemia (3 papers, 2021 to 2026). An increased concentration of glucose in the blood. "Our results indicate that transient high glucose causes persistent OXTR suppression during subsequent normoglycemia through hyperglycemia-mediated consistent oxidative stress." (PMID 33633538, 2021). "Our results indicate that hyperglycemia induces OXTR suppression through decreased association of ERE on the OXTR promoter." (PMID 33633538, 2021). "On one hand, in vitro experiments and in vivo pharmacologic experiments provided evidence that under hyperglycemia, OXTR activation can potentiate insulin secretion and glucose suppression." (PMID 39764245, 2024). "In vitro experiments and in vivo pharmacologic experiments provided evidence that under hyperglycemia, OXTR activation can potentiate insulin secretion and glucose suppression." (PMID 39764245, 2024). "In this study, we found that OXTR is suppressed by hyperglycemia-mediated epigenetic changes and the subsequent dissociation of ERβ from the OXTR promoter." (PMID 33633538, 2021). "The results showed that ERβ lentivirus manipulation was successful and that ERβ expression completely reversed, while ERβ knockdown mimicked hyperglycemia [HG(4d) + LG(4d)/CTL group]-induced OXTR suppression, compared to the LG(4d) + LG(4d)/CTL control group." (PMID 33633538, 2021). "Our in vitro study of human neuron progenitor cells showed that hyperglycemia induces OXTR suppression and that this suppression remains during subsequent normoglycemia." (PMID 33633538, 2021). "Further investigation found that OXTR suppression is due to hyperglycemia-mediated epigenetic changes on the OXTR promoter and subsequent dissociation of ERβ from the OXTR promoter." (PMID 33633538, 2021). "Our results indicate that hyperglycemia induces OXTR suppression through epigenetic modification and the subsequent dissociation of ERβ from the OXTR promoter." (PMID 33633538, 2021). "Further investigation showed that OXTR suppression is due to hyperglycemia-induced persistent oxidative stress and epigenetic methylation in addition to the subsequent dissociation of estrogen receptor β (ERβ) from the OXTR promoter." (PMID 33633538, 2021). "Oxytocin receptor is suppressed by hyperglycemia-induced persistent oxidative stress and epigenetic changes, which can be inherited during subsequent normoglycemia." (PMID 33633538, 2021). "Our in vitro study in human neuron progenitor cells showed that OXTR expression was suppressed by transient high glucose levels and remained low during subsequent normoglycemia through hyperglycemia-mediated consistent oxidative stress." (PMID 33633538, 2021). "In mice treated with the cytotoxic agent, streptozotocin, deletion of OXTR resulted in greater hyperglycemia in β-KO mice relative control mice, suggesting that β-cell OXTR may provide some cytoprotection." (PMID 39764245, 2024). "Finally, β-cell OXTR protects against STZ-induced hyperglycemia, presumably by attenuating cytotoxicity." (PMID 39764245, 2024). "We investigated the possible molecular mechanism for hyperglycemia-mediated OXTR suppression." (PMID 33633538, 2021). "Further investigation showed that hyperglycemia-induced OXTR suppression is due to oxidative stress-mediated consistent histone methylation on the OXTR promoter, indicating that these types of epigenetic changes can be inherited in offspring as a result of maternal diabetes." (PMID 33633538, 2021). "In addition, our study has shown that hyperglycemia-induced histone methylation dissociates ERβ from the OXTR promoter and subsequently resulting in OXTR down-regulation." (PMID 33633538, 2021). "We also evaluated histone H4 methylation on the OXTR promoter and found that hyperglycemia did not have any effect on histone H4 methylation." (PMID 33633538, 2021). "We found that hyperglycemia suppresses the expression of both OXT and OXTR, and OXTR expression remains low, while OXT expression returns to normal during subsequent normoglycemia." (PMID 33633538, 2021).
Infertility (3 papers, 2023 to 2024). "Since oxytocin plays a possible role in male reproductive function and infertility through the oxytocin/oxytocin receptor (OT/OTR) system, it is conceivable that this exerkine could have positive effects on the treatment of male infertility." (PMID 39335489, 2024).
viral infections (3 papers, 2017 to 2023). "Extrapolating these data, we asked whether OXTR downregulation would generally be caused by viral infections in humans and analyzed published GEO databases from human studies that focused on different viral infections (HIV, SIV, influenza virus, etc.)." (PMID 28506310, 2017). "It is also worth mentioning that the expression of the OXTR gene, and thus the abundance of OXTR, can be significantly modulated by external factors, such as viral infections and inflammatory processes." (PMID 36835321, 2023). "More specifically, these data suggest a skewing from OXTR/pERK to TGF-β/pSmad3 signaling upon viral infections, which is reminiscent of the age-imposed changes that associate with broad degenerative pathologies." (PMID 28506310, 2017). "The general effects of viral infections on OXTR downregulation in humans were also examined by analyzing published Gene Expression Omnibus (GEO) datasets." (PMID 28506310, 2017). "In this regard, our data suggest that viral infections will decrease muscle and bone maintenance and repair, as well as the sense of well-being and psychological health, all of which rely on OXTR signaling." (PMID 28506310, 2017). "Furthermore, an examination of published datasets uncovered similar OXTR downregulation in humans that are afflicted with different viral infections." (PMID 28506310, 2017). "Interestingly, this analysis confirmed and extrapolated our conclusions by revealing that OXTR becomes significantly downregulated upon different unrelated viral infections in human populations." (PMID 28506310, 2017). "Furthermore, we mined published data for the influence of viral infections on OXTR levels in human populations and found that unrelated viral pathologies have a common consequence: diminished levels of OXTR." (PMID 28506310, 2017). "And it further implicates that viral infections may play a role in decreasing OXTR and thus broadly interfering with regeneration and maintenance of multiple tissues." (PMID 28506310, 2017). "In addition to pooling the results from all databases, the data from each individual database were also examined: for each group, OXTR showed downregulation upon viral infections ranging from 47 to 82%, as compared with the level of this receptor in healthy individuals." (PMID 28506310, 2017). "Skewing from OXTR to TGF-β/pSmad is predicted to diminish the maintenance and repair of skeletal muscle (and possibly, other tissues), and accordingly, control viral infections diminish myogenicity." (PMID 28506310, 2017). "At later stages of infection, VZV downregulated various other types of cell surface receptors, including the oxytocin receptor (OXTR), GDNF family receptor alpha-1 (GFRA1) and the poliovirus receptor (PVR; CD155), suggesting a more broad effect of virus infection on cell surface receptors." (PMID 32547533, 2020). "While we show that viral infections and experimental transductions do not broadly attenuate all cell-surface receptors, it is likely that more than just OXTR becomes downregulated." (PMID 28506310, 2017).
Anorexia (2 papers, 2013 to 2022). Lack of desire to eat (loss of appetite). "Genetic studies have also shown that there is nucleotide polymorphism in both the oxytocin receptor gene and the oxytocin gene, which is associated with pathologies that involve hyperphagia, anorexia, and bulimia." (PMID 35888641, 2022). "A nonselective antagonist that blocks either oxytocin receptor or vasopressin V1 receptor 39 has been shown to increase meal size 40 and activation of vasopressin V1 receptors induces anorexia 41,42." (PMID 23363338, 2013).
asthma (2 papers, 2010 to 2015). "Among the top genes are ones that have been previously related to asthma (e.g., APOE, CHI3L1, EGR1, MYH11, OXTR, SERPINB2, SOCS3) and corticosteroid-resistant asthma (e.g., FOS) though not necessarily in humans or via changes of the ASM." (PMID 26207385, 2015).
Dysmenorrhea (2 papers, 2014 to 2017). Pain during menstruation that interferes with daily activities. "Combining with oxytocin, excessive and irregular oxytocin receptor causes higher intrauterine pressure which is related to dysmenorrhea." (PMID 28049501, 2017).
dystocia (2 papers, 2010 to 2022). Slow or difficult obstetric labor or childbirth. "Initially, we sequenced all OXT and OXTR exons including splice sites and putative promoter regions in five individuals with dystocia and one control to detect common variations." (PMID 20587075, 2010).
generalized anxiety disorder (2 papers, 2025). An anxiety disorder characterized by excessive and difficult-to-control worry about a number of life situations. "This study aimed to investigate whether the functional OXTR rs2254298 polymorphism moderates escitalopram response in Generalized Anxiety Disorder (GAD) through oxytocin (OT) neuroendocrine signaling, with specific consideration of sex-specific effects." (PMID 41356682, 2025).
leiomyoma (2 papers, 2010 to 2023). A well-circumscribed benign smooth muscle neoplasm characterized by the presence of spindle cells with cigar-shaped nuclei, interlacing fascicles, and a whorled pattern. "ST images showed that OXTR and AVPR1A were highly expressed in pseudocapsule area instead of leiomyoma area." (PMID 37215998, 2023). "The leiomyoma-derived fibroblasts were negative for the oxytocin receptor (OTR), indicating that the FB were not uterine smooth muscle cells." (PMID 20537183, 2010). "Besides AVPR1A and OXTR, we further found PTGER3, one of top DEGs, was highly expressed on the smooth muscle cells in pseudocapsule compared to leiomyoma, indicated that PGE2 might be another candidate." (PMID 37215998, 2023).
malignant melanoma (2 papers, 2021). "Oxytocin receptor (OXTRs) expression is upregulated in malignant melanoma." (PMID 34988010, 2021). "Results suggest that OXTR-induced microenvironment can promote mammary-specific tumor growth and metastasis but not melanoma tumors." (PMID 34099636, 2021). "In vitro, activation of oxytocin receptor (OXTRs) promotes migration, invasion and angiogenesis of melanoma cells through the Arrestin2-dependent ERK-VEGF/MMP-2 pathway, but does not promote proliferation of melanoma cells." (PMID 34988010, 2021).
metastatic carcinoma (2 papers, 2019). A carcinoma which has spread from the original site of growth to another anatomic site. "They together strongly support the inhibitory role of OXTR signaling in metastatic cancers, including CAC." (PMID 31920487, 2019).